TTR (transthyretin)
Diseases named in the same sentence as TTR in open-access papers (continued):
Sharing a sentence is not in itself a finding about the gene and the disease.
amyloidosis (continued). "Inotersen is an antisense oligonucleotide (ASO) for ATTRv amyloidosis that targets TTR mRNA and induces degradation, preventing RNA translation and expression of both wild-type and mutant TTR." (PMID 37901600, 2023). "The patient is a 67 year old male with a history of multiple HF hospitalizations due to an established diagnosis of wild type TTR-Amyloidosis for at least 6 years, with significant cardiac involvement requiring dobutamine and diuretic infusions." (PMID 36769832, 2023). "Because transthyretin is mainly produced in the liver, liver transplantation has been the standard treatment for ATTRv amyloidosis since the 1990s." (PMID 37828588, 2023). "Several natural compounds are listed as inhibitors of transthyretin amyloidosis and neuroprotective agents, but, currently, there are only few TTR ligands approved or under investigation for the ATTR pharmacological therapy." (PMID 38203650, 2023). "Classifications include primary light chain (AL), secondary senile amyloid A (AA), transthyretin (TTR) amyloidosis, dialysis-related, and systemic amyloidosis of poorly understood etiology." (PMID 37485202, 2023). "The formulation that inhibits transthyretin protein formation in the liver recently received FDA approval to treat hereditary transthyretin‐mediated amyloidosis." (PMID 37166046, 2023). "Multimodality imaging with echocardiogram and bone tracer cardiac scintigraphy along with biomarkers, monoclonal proteins analysis and genetic test allowed to diagnosed a wild-type transthyretin amyloidosis." (PMID 36751253, 2023). "In TTR amyloidosis, the primary outcome occurred in 99 (65%) patients, including 47 deaths (30 from cardiovascular causes) and 53 HF hospitalizations." (PMID 37600055, 2023). "Taken together, this study elucidates the role of EGCG in preventing TTR amyloidosis, which can provide important theoretical support for the future of drug design for ATTR." (PMID 37762449, 2023). "Age-related (wtATTR; senile) amyloidosis is a result of tissue infiltration with the wild-type transthyretin protein." (PMID 36968873, 2023). "The dissociated TTR will further misfold and aggregate, triggering transthyretin amyloidosis (ATTR) as a result." (PMID 37762449, 2023). "The common types that preferentially involve the heart are amyloid light-chain (AL) (primary) amyloidosis, familial transthyretin amyloid (mATTR) (hereditary) amyloidosis, and wild-type ATTR (senile systemic) amyloidosis." (PMID 36968873, 2023). "The Patisiran (ONPATTRO®) was proposed for the medication of hereditary transthyretin-mediated amyloidosis by targeting a sequence of transthyretin-mRNA." (PMID 37848888, 2023). "The results were then confirmed in a phase 2 open-label, single-treatment arm study enrolling patients with non-Val30Met TTR amyloidosis." (PMID 37288260, 2023). "Another two patients (0.6%) received patisiran, a transthyretin (TTR)-directed double-stranded, small interfering RNA, for the treatment of the polyneuropathy of hereditary TTR-mediated amyloidosis (hATTR)." (PMID 36837468, 2023). "In transthyretin amyloidosis, systemic symptoms arise from breaking the tetrameric structure into monomers of the transthyretin (TTR) plasma protein." (PMID 38288300, 2023). "Different therapies have been approved for ATTRv amyloidosis so far, including the TTR stabilizer tafamidis and, more recently, the RNAi agent patisiran and the antisense oligonucleotide inotersen." (PMID 36064814, 2023). "The 21 bp long Patisiran is one of the few approved therapeutic siRNA molecules and is used to treat hereditary transthyretin amyloidosis by knocking down transthyretin mRNA (both mutant form and wild type) produced in the liver." (PMID 36512308, 2023). "It is the first siRNA-based drug used for the treatment of polyneuropathy in people with hereditary transthyretin (TTR)-mediated amyloidosis, a rare and fatal condition." (PMID 36833241, 2023).
amyloidosis (continued). "A phase II, open-label study demonstrated that doxycycline (100 mg twice/day) and TUDCA (250 mg three times/day) administered continuously for 12 months in patient with TTR-amyloidosis (FAP and/or CM) stabilized the disease for at least 1 year." (PMID 37288260, 2023). "Approximately 13% of HFpEF patients suffer from wild-type transthyretin (TTR) amyloidosis stemming from increased cardiac protein deposition." (PMID 37362441, 2023). "Our case highlights that early detection and accurate diagnosis of a disease are important factors for improving clinical outcomes in patients with TTR amyloidosis." (PMID 36837536, 2023). "Temporal changes of patient characteristics with respect to gender, age and comorbidities suggest wild-type transthyretin amyloidosis as the main driver of increasing incidence." (PMID 36241897, 2023). "TTR can be responsible for several amyloidosis diseases, such as familial amyloid polyneuropathy (FAP), familiar amyloid cardiomyopathy (FAC), central nervous system amyloidosis (CNSA), and senile systematic amyloidosis (SSA)." (PMID 36771455, 2023). "The main objective of this study was to evaluate the impact of a vial-sharing strategy for patisiran, an orphan drug used for the treatment of hereditary transthyretin-mediated amyloidosis, in terms of a reduction in the discarded drug amount and cost savings." (PMID 37046940, 2023). "Inotersen reduces transthyretin production, thereby decreasing amyloid formation and alleviating the symptoms of hATTR amyloidosis." (PMID 36833241, 2023). "While this protein and its associateddiseases have been researched for a long time, there is currentlyno clinically approved TTR-based biomarker for TTR amyloidosis inblood plasma or cerebrospinal fluid." (PMID 37477604, 2023). "CFVR measured with TTDE is significantly lower in patients with amyloidosis (both transthyretin and light chain) compared to control subjects, and a strong relation is seen between physical capacity and CFVR in this group of patients." (PMID 36673004, 2023). "TTR research to understand protein misfolding diseases is ofconsiderable interest due to the impact of TTR amyloidosis on theafflicted ATTR patient and society." (PMID 36780206, 2023). "The patient had a history of multiple HF hospitalizations due to an established diagnosis of wild type TTR-Amyloidosis with significant cardiac involvement." (PMID 36769832, 2023). "Among them, Tafamidis has been approved in many countries for the treatment of patients with ATTRv amyloidosis by stabilizing its tetramer via binding to two sites of TTR and inhibiting amyloid fibril formation." (PMID 36311011, 2022). "SSA is a common, age-related, amyloidosis characterized by the accumulation of wt-TTR fibrils, predominantly in the heart and, to a lesser extent, in other organs." (PMID 35337074, 2022). "Transthyretin-amyloidosis occurs due to the accumulation of transthyretin-amyloid in the extracellular space of various organs and systems, especially the heart and nervous system." (PMID 36361589, 2022). "In August 2021, vutrisiran was enrolled in the phase III study (HELIOS-B) for the treatment of TTR-mediated Amyloidosis with patients having cardiomyopathy." (PMID 35352626, 2022). "The first siRNA medication, patisiran, was approved by the United States (US) Food and Drug Administration (FDA) in 2018 for the treatment of transthyretin amyloidosis by targeting the 3′UTR of the transthyretin mRNA." (PMID 35755805, 2022). "There are different subtypes of amyloidosis, with the most common being immunoglobulin-derived acquired light chain amyloidosis (AL amyloidosis) and transthyretin (TTR) amyloidosis, the latter being the most common hereditary form." (PMID 36341129, 2022).
amyloidosis (continued). "Looking at the development of animal models for TTR related amyloidosis over the years, it appears that we moved from complicated living organisms (i.e., mice) to quite simpler invertebrate models, such as C. elegans and Drosophila and, finally back to mice." (PMID 35237660, 2022). "Patisiran, the first approved RNAi (in 2018) for the treatment of hereditary transthyretin-mediated amyloidosis (hTTR), acts by targeting the untranslated region of TTR mRNA, reducing translation of its protein." (PMID 35890248, 2022). "The amyloidosis TTR-related symptoms are also determined by unclear mechanisms apart from mutations in the TTR gene and in some other known genes." (PMID 36289657, 2022). "Wild-type (wt) transthyretin amyloidosis (ATTR) is a disease that involves the accumulation of protein deposits in cardiac muscle fibers, causing heart failure in elderly people." (PMID 36071866, 2022). "The most recently approved siRNA is AmvuttraTM (vutisiran) for treatment of the polyneuropathy of hereditary transthyretin-mediated amyloidosis (June 2022)." (PMID 36401279, 2022). "Transthyretin amyloidosis (ATTR) exists as two subtypes ‐ age related, also known as wild type TTR (ATTRwt), and an inherited form, also known variant ATTR (ATTRv), which differ in age of onset and disease penetrance." (PMID 35024457, 2022). "Patisiran is used for the treatment of polyneuropathy in people with the genetic disorder, hereditary transthyretin‐mediated amyloidosis.[80a] Two more of Alnylam's siRNA therapeutics quickly followed into the clinic." (PMID 35941991, 2022). "Comprehensive research studies recently discovered the presence of intramyocardial amyloidosis in HFpEF, which is characterised by deposition of wild-type transthyretin localised in the left ventricle." (PMID 36291628, 2022). "Since the approval of the first siRNA therapeutic, ONPATTROTM (Patisiran), for the treatment of transthyretin‐mediated amyloidosis, more and more siRNA therapeutics are under clinical trials for diverse diseases, especially cancers." (PMID 35696608, 2022). "ATTR amyloidosis is characterized by the misfolding of TTR monomers and their accumulation within tissues as amyloid fibres." (PMID 35386059, 2022). "This process was first approved in 2018 for an anti-transthyretin siRNAfor treatment of amyloidosis." (PMID 39076655, 2022). "The first small interfering (si)RNA-based therapy was approved by the Food and Drug Administration (FDA) in 2019 for the treatment of polyneuropathy in people with hereditary transthyretin (TTR)-mediated amyloidosis." (PMID 35409184, 2022). "There are various studies proposing the effect of non-coding cis- and trans-acting regulatory genetic factors on the TTR expression and tissue-specific amyloid formation, as well as the age at disease onset." (PMID 35463150, 2022). "Hereditary transthyretin (ATTRv) amyloidosis is a rare, life-threatening autosomal-dominant systemic disorder characterized by extracellular deposition of misfolded transthyretin fibrils in various tissues." (PMID 36494773, 2022). "Two major forms of ATTR amyloidosis are recognized: wild-type ATTR (ATTRwt) and variant ATTR (ATTRv; due to point mutations in the TTR gene) amyloidosis." (PMID 36551810, 2022). "In 2018, patisiran, the first mRNA drug for treating hereditary transthyretin-mediated amyloidosis, was encapsulated by cationic lipid nanoparticles and achieved significant success." (PMID 35335310, 2022). "Hereditary transthyretin-mediated (hATTR) amyloidosis with polyneuropathy is a rare, inherited, multisystem, and often fatal disease caused by a variant in transthyretin (TTR) gene." (PMID 34755769, 2022). "Current therapeutic options rely on the blockade of TTR production, TTR stabilization to maintain the native structure of TTR, amyloid degradation, or induction of amyloid removal from tissues." (PMID 35386059, 2022).
amyloidosis (continued). "A variety of soluble proteins, including amyloid-β (Aβ), α-synuclein (α-syn), transthyretin (TTR), β2-microglobulin (β2-MG), and serum amyloid A (SAA) are aggregated and deposited in the body, causing amyloidosis." (PMID 35402512, 2022). "Amyloid light-chain (AL) and transthyretin (ATTR) amyloidoses are the most common forms of cardiac amyloidosis." (PMID 36551810, 2022). "Injecting anti-transthyretin siRNA encapsulated by DLin-MC3-DMA reduced the transthyretin level by 60% in transthyretin amyloidosis patients." (PMID 36507276, 2022). "On the other hand, the excess of circulating TTR provides a favorable environment for the transthyretin amyloidosis involved in numerous ophthalmological pathologies." (PMID 36498980, 2022). "Although the exact epidemiological figure of transthyretin (ATTR) amyloidosis is still under scrutiny, this condition is more prevalent than traditionally thought, being reported in the heart of 25–40% of unselected adults > 75 years." (PMID 36419501, 2022). "We have demonstrated that myocardial 18F-fluoride PET uptake is increased in patients with TTR amyloid, with TBR values providing quantification and clear discrimination from other similar conditions such as AL amyloid and aortic stenosis." (PMID 33000405, 2022). "Onpattro represents the first clinically approved cationic liposomal formulation encapsulating siRNA to sequester and silence transthyretin for treatment in hereditary transthyretin-mediated amyloidosis." (PMID 35822814, 2022). "LNPs have been used for the development of Onpattro, an siRNA drug for transthyretin-mediated amyloidosis, in 2018." (PMID 36286056, 2022). "The correlation of TTR concentrations in urine versus the ATTRv score, even in patients at early-stage ATTRv amyloidosis, is much stronger than that of the albumin concentrations and creatinine levels." (PMID 35893595, 2022). "This crystal structure provides a structural basis for the clinically observed interactions of similar phenylanthranilic acids (e.g., flufenamic acid) with TTR and provides a template for the design of TTR stabilizers for the prevention of TTR amyloidosis." (PMID 36364032, 2022). "Amyloid transthyretin (ATTR) amyloidosis is a clinically heterogeneous and fatal disease that results from deposition of insoluble amyloid fibrils in various organs and tissues, causing progressive loss of function." (PMID 33609196, 2022). "Meanwhile, IAPP fibrils were considered to be interacted with transthyretin, which further resulted in amyloid fibrosis deposition and eventually gave rise to the decreased percentage of pancreatic β-cells." (PMID 35889910, 2022). "Lastly, patients with hereditary transthyretin-mediated amyloidosis with polyneuropathy had significantly increased levels of NFL (SMD, 0.93 [95% CI, 0.66 to 1.20]; P = .002; I2 = 0%) compared with controls." (PMID 36574244, 2022). "Most notably, Patisiran, a liposomal based siRNA targeting transthyretin, was recently approved by the FDA and European Commission for the treatment of hereditary transthyretin-mediated amyloidosis in adults." (PMID 36015246, 2022). "The follow-up of patients affected by severe forms of systemic ATTRv amyloidosis who underwent liver transplantation as curative therapy provided us with data on human turnover of tissue TTR amyloid." (PMID 36009453, 2022). "Hereditary transthyretin amyloidosis (hATTR/ATTRv) results from the deposition of misfolded transthyretin (TTR) throughout the body, including peripheral nerves." (PMID 35908242, 2022). "The main types of cardiac amyloidosis are immunoglobulin light chain (AL) and transthyretin (ATTR) amyloidosis." (PMID 35892668, 2022). "TTR proteolysis has recently attracted attention due to its implications for TTR instability and the pathogenesis of amyloidosis." (PMID 36009453, 2022).
amyloidosis (continued). "Urinary TTR concentrations were significantly higher in the ATTRv V50M amyloidosis patients than they were in the healthy volunteers and asymptomatic carriers of the gene." (PMID 35893595, 2022). "It was approved for treatment of patients with hereditary transthyretin-mediated amyloidosis and consists of a 21-mer double-stranded siRNA (ALN-18328) encapsulated in four lipid excipients." (PMID 35687098, 2022). "This approach combines the accurate diagnosis of cardiac amyloid on the CMR with clear discrimination of biopsy proven AL and TTR amyloid on the 18F-fluoride PET in a single scan." (PMID 33000405, 2022). "Patisiran and vutrisiran are other FDA-approved RNA therapies to prevent TTR synthesis in individuals with hereditary transthyretin amyloidosis and were designed as small double-stranded RNAis with lipid NPs and GaINAc delivery particles, respectively." (PMID 36365206, 2022). "In the present review, we summarize the current knowledge on the proteolytic susceptibility of three of the main human amyloidogenic proteins, i.e., transthyretin, β-amyloid precursor protein, and α-synuclein, in the onset of amyloidosis." (PMID 36614141, 2022). "Transthyretin(TTR)-amyloidosis (hereditary or wild-type) is characterized by deposition of misfold, insoluble amyloid fibrils in the interstitial space, leading to dysfunction of the involved organs." (PMID 35925120, 2022). "In this context, the first siRNA-based therapy approved by FDA is patisiran, for patients with transthyretin-mediated amyloidosis." (PMID 35807171, 2022). "TTR amyloidosis is a conformational disease and the pathologic protein aggregation is largely due to reduced folding stability." (PMID 33188616, 2022). "In all amyloidosis referral centers, we are witnessing a substantial increase in the prevalence of wild-type transthyretin (ATTRwt) cardiomyopathy, which is now becoming the most frequent form of cardiac amyloidosis." (PMID 36555787, 2022). "Several studies conducted on ATTRv and/or ATTRwt amyloidosis patients showed that TTR amyloid deposition manifests organ and tissue tropism, suggesting that the mechanism of TTR fibril deposition is closely related to the surrounding microenvironment." (PMID 36009453, 2022). "Some mutations in the coding gene, i.e. TTR, cause hereditary ATTR (ATTRv) amyloidosis, in which the TTR tetramer is more prone to dissociate, thus leading to an earlier onset of disease." (PMID 36302762, 2022). "TTR amyloid deposition has been well documented as occurring frequently in the urinary tract, including the bladder, in ATTRv amyloidosis." (PMID 35893595, 2022). "The ability of tolcapone to cross the blood–brain barrier and its potential to bind to TTR within the cerebrospinal fluid make this drug particularly attractive for repurposing efforts aimed at treating ATTRv amyloidosis with leptomeningeal involvement." (PMID 36555787, 2022). "Tissue biopsy was taken from the LF at the affected level and was stained with special immunohistochemical stain to detect transthyretin (TTR)-related amyloidosis (ATTR)." (PMID 35911371, 2022). "The FDA approval of patisiran, an siRNA for the treatment of patients with hereditary transthyretin-mediated amyloidosis, points towards the great potential of RNA interference therapeutics." (PMID 35578240, 2022). "Similar results were observed in mouse models of TTR amyloid disease, where age-dependent deposition of TTR aggregates in the heart correlated with aberrant expression of proteostasis factors in the liver." (PMID 35191945, 2022). "Amyloid TTR (ATTR) amyloidosis is among the most common forms of amyloidosis in human pathology, and it can present as a hereditary form caused by TTR mutations (variant ATTR, ATTRv) or acquired ones due to the deposition of TTR wild-type (ATTRwt)." (PMID 36009453, 2022). "It has been reported that rupture of the distal biceps tendon was found in 33.3% of patients with wild-type transthyretin amyloidosis cardiomyopathy." (PMID 35645614, 2022).